GLIDR (glioblastoma down-regulated RNA)
Synonyms: MGC21881; TCONS_00015562; FAM88A; LINC01172
Gene: Long non-coding RNA gene on chromosome 9 (39,705,825 to 39,810,128, reverse strand). Ensembl gene ENSG00000278175.
Diseases named in the same sentence as GLIDR in open-access papers:
GLIDR is named in the same sentence as 4 diseases in open-access papers, as found by Europe PMC text mining. Sharing a sentence is not in itself a finding about the gene and the disease. The quoted sentences say what the papers report.
glioblastoma (2 papers, 2020 to 2022). The most malignant astrocytic tumor (WHO grade IV). "The following lncRNAs engaged in glioblastoma therapy resistance were selected: MALAT1, CASC2, H19, TUSC7, XIST, RP11-838N2.4, DLX6-AS1, GLIDR, MIR210HG, SOX2-OT." (PMID 33245508, 2022).
glioma (2 papers, 2017 to 2023). A benign or malignant brain and spinal cord tumor that arises from glial cells (astrocytes, oligodendrocytes, ependymal cells). "GLIDR is upregulated and promotes glioma, lung, and prostate cancers by acting as competing endogenous RNAs for miRNAs." (PMID 37445988, 2023).
tumor (2 papers, 2020 to 2022). "Differential expression analysis revealed significant divergence in lncRNA profile between parental tumors and tumor-derived cell cultures in vitro, including the following particles: MALAT1, CASC2, H19, TUSC7, XIST, RP11-838N2.4, DLX6-AS1, GLIDR, MIR210HG, SOX2-OT." (PMID 33245508, 2022).
GLIDR also shares sentences with these, for which no sentence is quoted: cancer (2 papers).